ENSG00000286971 (novel transcript)
Gene: Long non-coding RNA gene on chromosome 2 (127,024,738 to 127,034,887, forward strand). Ensembl gene ENSG00000286971.
Gene Ontology:
Biological process: SRP-dependent cotranslational protein targeting to membrane, signal sequence recognition
Cellular component: signal recognition particle, endoplasmic reticulum targeting